TEAD1 (TEA domain transcription factor 1)
Diseases named in the same sentence as TEAD1 in open-access papers (continued):
Sharing a sentence is not in itself a finding about the gene and the disease.
glioblastoma (8 papers, 2015 to 2024). The most malignant astrocytic tumor (WHO grade IV). "More recently, it was found that the compound NSC682769, a benzazepine derivative, at submicromolar concentrations inhibited YAP/TEAD1 (TEA domain family member 1) interaction in glioblastoma cells." (PMID 35053254, 2022). "For example, utilizing ATAC-seq to explore the differences in chromatin accessibility between neural stem cells and tumor-specific/migratory stem cells, TEAD1 (TEA domain family member 1) has been identified as a regulator of migration in glioblastoma." (PMID 34732244, 2021). "Here the authors purify GBM stem cells (GSCs) from patients and profile chromatin accessibility in these cells, identifying TEAD1 as a regulator of migration in human glioblastoma." (PMID 30275445, 2018). "This further argues that YAP1 association with chromatin is mainly mediated via TEAD TFs and specifically by TEAD1 in the tested glioblastoma setting." (PMID 26295846, 2015). "For example, miR-124 alleviates cell death in the process of AD by targeting BACE1, while increases cell death in glioblastoma by regulating TEAD1, MAPK14/p38α, and SERP1." (PMID 26041995, 2015). "In silico analysis of the downstream Hippo signalling members YAP1, TAZ and TEAD1 transcript levels in low‐grade glioblastoma (LGG) and GBM tumour tissues was performed using GEPIA." (PMID 39718433, 2024). "Indeed, we found migratory deficits in TEAD1 knockout GBM cells not only in vitro but also in patient-derived xenografts, strengthening the role of this TF for promoting infiltrative spread in human glioblastoma." (PMID 30275445, 2018).
hepatocellular carcinoma (8 papers, 2017 to 2025). A malignant tumor that arises from hepatocytes. "Previous studies have discovered that TEAD1 is associated with cancers, including glioma, hepatocellular carcinoma and clear cell renal cell carcinoma." (PMID 37752588, 2023). "We further constructed a prognostic model for hepatocellular carcinoma using 22 disulfide apoptosis genes that were significantly positively correlated with TEAD1." (PMID 40539054, 2025). "We first verified the significantly high expression of TEAD1 in hepatocellular carcinoma in additional GEO datasets." (PMID 40539054, 2025). "Another study showed that circGPRC5A can bind miR-1283 and activate the YAP1/TEAD1 signaling pathway to promote the growth of hepatocellular carcinoma." (PMID 38057879, 2023). "In LIHC, the significant correlation between TEAD1and malignant cells highlights the multifaceted roles that TEAD1 may play in hepatocellular carcinoma, including its potential as both a biomarker and therapeutic target." (PMID 40539054, 2025). "In addition, circGprc5a contributes to hepatocellular carcinoma progression by binding with miR-1283 to activate the YAP1/TEAD1 signaling pathway." (PMID 35415250, 2022). "In hepatocellular carcinoma (HCC), MALAT1-upregulated SRSF1 enhances the isoforms of the antiapoptotic gene BIM and the oncogenes S6K1 and TEAD1, leading to cancer cell proliferation, survival, and tumorigenesis." (PMID 32967226, 2020).
Chorioretinal atrophy (7 papers, 2012 to 2025). Atrophy (wasting) of the choroid and retinal layers of the fundus. "We describe a case of a Puerto Rican female patient with a heterozygous TEAD1 variant (c.599C>T; p.Ala200Val), currently classified as a variant of uncertain significance, who presented with chorioretinal atrophy consistent with SCRA." (PMID 40984966, 2025). "Sveinsson’s chorioretinal atrophy is an eye disorder that is characterised by bilateral chorioretinal degeneration and is linked to a mutation in TEAD1 that abolishes its interaction with YAP." (PMID 33233821, 2020). "For example in family 19, a novel multiexon duplication in TEAD1 was detected with an associated clinical phenotype consistent with Sveinsson chorioretinal atrophy (OMIM #108985)." (PMID 32783370, 2020). "Another locus of interest in the secondary analysis of subjects with hypertension included SNPs near TEAD1 on chromosome 11, a gene associated with peripapillary chorioretinal degeneration." (PMID 23393555, 2013). "Family 19 were found to have a novel heterozygous multi‐exon (exons 1–8) duplication in TEAD1 displaying a clinical phenotype consistent with Sveinsson chorioretinal atrophy." (PMID 32783370, 2020). "Despite its current classification as a variant of uncertain significance, the patient's phenotype, including bilateral peripapillary chorioretinal atrophy, centrifugal extension toward the macula, and early macular thinning on OCT, closely aligns with previously reported pathogenic TEAD1 mutations." (PMID 40984966, 2025).
dilated cardiomyopathy (7 papers, 2019 to 2025). Cardiomyopathy which is characterized by dilation and contractile dysfunction of the left and right ventricles. "TEAD1 trapping by mutant Lamin A/C causes dilated cardiomyopathy by dysregulation of cardiomyocyte structure genes." (PMID 37058558, 2023). "We demonstrated that Tead1 had a critical function in adult cardiomyocytes and that its loss of function leads to rapid-onset severe dilated cardiomyopathy." (PMID 30811446, 2019). "From the TEAD TF family, TEAD1 was enriched, documented for its expression in adult mammalian hearts and association with normal heart contractility where its mutations can lead to dilated cardiomyopathy." (PMID 39838281, 2025). "In addition to known associations, our analysis also identified novel regulators, including the identification of TFs FPM315 and OVOL2, which are implicated in dilated cardiomyopathies, and TEAD1 and TEAD2 in both dilated and ischemic cardiomyopathies." (PMID 38673810, 2024). "Our results demonstrated that cell-autonomous Tead1 function in cardiomyocytes was critical and its loss of function led to lethality by postnatal day 9, accompanied by significantly reduced cardiomyocyte proliferation, as well as systolic dysfunction and dilated cardiomyopathy." (PMID 30811446, 2019). "Perinatal Tead1 deletion was lethal by postnatal day 9 in Tead1-cKO mice due to dilated cardiomyopathy." (PMID 30811446, 2019). "In all, the echocardiographic analyses indicated that Tead1-cKO pups showed significant left ventricular systolic dysfunction and displayed features of chamber enlargement, consistent with dilated cardiomyopathy (DCM)." (PMID 30811446, 2019). "Supportive to this notion also comes from studies on the cardiomyocyte-restricted genetic interventions that either activate Mst1 (i.e. Mst1-TG) 19, 21 or suppress YAP or TEAD1 (i.e. YAP- or TEAD1-gene deletion) 23, 24, 51, all result in dilated cardiomyopathy with significant interstitial fibrosis." (PMID 36632235, 2023).
glioma (6 papers, 2018 to 2025). A benign or malignant brain and spinal cord tumor that arises from glial cells (astrocytes, oligodendrocytes, ependymal cells). "Nevertheless, we did observe lasting downregulation of several TEAD-accessible genes previously implicated in glioma migration, consistently across TEAD1-knockout cell lines and spheroids, including AQP447–49, CDH1146, MMP1669, SEMA3A70, and CDK1471." (PMID 30275445, 2018). "To evaluate selective target modulation by YTPs in cellular systems, we engineered a stable YTP-resistant TEAD1V406A/E408A variant of the TEAD1-dependent, YAP-amplified glioma line SF-268, which maintains its interaction with endogenous YAP and TAZ." (PMID 38565920, 2024). "Differential expression analysis based on all cancer and normal samples from TCGA also confirmed the high expression of TEAD1 in cancers including CHOL, glioma (GBM), and LIHC." (PMID 40539054, 2025). "Survival analysis showed that patients with high methylation levels of TEAD1 had better prognoses in GBM, LUSC, and skin cutaneous melanoma (SKCM), while the opposite was true in KIRC, lower grade glioma (LGG), and uveal melanoma (UVM)." (PMID 40539054, 2025). "At the protein level, we noted expression of TEAD1 but not of other TEAD members in PDX gliomas previously generated from acutely sorted GBM GSCs17." (PMID 30275445, 2018).
lung carcinoma (6 papers, 2020 to 2025). "Our analysis of lung cancer context-specific interaction networks of hub genes revealed that deregulated expressions of EGFR/MAP2K1/mTOR/TEAD1/YAP1 in lung cancer mediated abnormal expressions of 151 genes in total in 154 cancer-mediated interactions." (PMID 35655775, 2022). "Furthermore, we found that expression levels of these genes were associated with tumor metastasis; MAP2K1, mTOR, and TEAD1 were significantly overexpressed, while YAP and EGFR were under-expressed in metastasized lung cancer compared to primary tumors." (PMID 35655775, 2022). "Interestingly, we found that high expression levels of EGFR/MAP2K1/mTOR/TEAD1/YAP1 in lung cancer significantly decreased overall levels of active cytotoxic lymphocytes, mediated dysfunctional T-cell phenotypes, and produced worse overall survival rates of lung cancer cohorts." (PMID 35655775, 2022). "Genetic alterations of EGFR, MAP2K1, mTOR, TEAD1, and YAP1 in The Cancer Genome Atlas (TCGA) cohorts of lung cancer occurred at respective frequencies of 15.0%, 1.80%, 6.00%, 1.80%, and 2.50%." (PMID 35655775, 2022). "To further validate the role of IGFBP7 on the c-Fos/YAP/TEAD1/TEAD4 signaling axis in human lungs, we analyzed the expression of IGFBP7/c-Fos/YAP/TEAD1/TEAD4 in lung tissues of ARDS patients and para-cancerous tissues of lung cancer patients collected previously." (PMID 38840498, 2024). "Interestingly, we found that lung cancer cohorts with genetic alterations of EGFR, MAP2K1, mTOR, TEAD1, and YAP1 exhibited worse prognoses of overall, disease-specific, and progression-free survival compared to patients with wild-type (WT) genes." (PMID 35655775, 2022).
colorectal cancer (5 papers, 2017 to 2022). A primary or metastatic malignant neoplasm that affects the colon or rectum. "It has been proved that overexpression of TEAD1 increased the cellular proliferation in colorectal cancer (CRC)." (PMID 30213067, 2018). "A recent report showing that overexpression of TEAD1 increases colorectal cancer cell proliferation while its knockdown reduces it clearly supports our findings." (PMID 30120107, 2018). "Consistent to the previous study in colorectal cancer, TEAD1 could promote SP1 transcriptional activation and expression in LUAD cells." (PMID 35485206, 2022). "TEAD1 was reported to enhance the proliferation in colorectal carcinoma." (PMID 29228695, 2017).
melanoma (5 papers, 2022 to 2025). A malignant, usually aggressive tumor composed of atypical, neoplastic melanocytes. "Interestingly, melanomas dependent on TEAD1 tended to also depend on RAC1 according to Depmap CRISPR dependency scores." (PMID 36271142, 2022). "Of the 62 melanoma cell lines in the DepMap Portal, 17 are dependent upon TAZ, 2 are dependent upon YAP, 9 are dependent upon TEAD1, and 1 is dependent upon TEAD4." (PMID 38473214, 2024). "We selected TEAD1 and TEAD4 for analysis because they are the predominantly expressed TEAD paralogs in many cancer cell lines, including NCI-H226 and MSTO-211H58 and in SOX10 KO melanoma cells." (PMID 41193428, 2025). "Interestingly, Tead1 and the Tead co-activator Yap were undetectable in BMMs and RAW264.7 cells but were abundantly expressed in the mouse melanoma cell line B16F1, mouse embryonic fibroblasts (MEF), MSC, and the mouse fibroblast cell line L929." (PMID 38493144, 2024).
mesothelioma (5 papers, 2021 to 2025). A usually malignant and aggressive neoplasm of the mesothelium which is often associated with exposure to asbestos. "Most prominently, YAP activates ferroptosis in mesothelioma, and the underlying mechanism is that unphosphorylated YAP/TAZ translocates to the nucleus to interact with transcription factors, such as TEAD1–4, to transcribe target genes." (PMID 37773303, 2024). "Most notably, this includes YAP and TEAD1, with YAP's regulatory role most significantly determined in the mesothelioma cell line, NCI‐H2052 (top two p‐values, each < .0001) and TEAD1 also yielding a highly significant association (p < .0001) in the MSTO mesothelioma line." (PMID 36740402, 2023).
pancreatic cancer (5 papers, 2012 to 2024). "However, the mechanism of upregulated TEAD1 in pancreatic cancer is referred to less frequently." (PMID 38740637, 2024). "We found that with the prolong of effect time of 8 mg/ml SJAMP on the pancreatic cancer cells, YAP, TEAD1, and Survivin expression significantly decreased, but the levels of the Hippo upstream gene, MST1, and Caspase-9 increased." (PMID 28099921, 2017). "In pancreatic cancer, differential hydroxymethylation of genes related to pancreas development or function (GATA4, GATA6, PROX1, ONECUT1, MEIS2), and cancer pathogenesis (YAP1, TEAD1, PROX1, IGF1) have also been shown to reliably identify pancreatic cancer from peripheral blood samples." (PMID 36835649, 2023). "Interestingly, none of the expression patterns of the known TEAD1 cofactors such as YAP matched the expression of MSLN in pancreatic cancers or in other cell line models used here." (PMID 23029054, 2012).
bladder cancer (4 papers, 2012 to 2023). "The study also discussed that a modest but significant increase in Livin is observed in other types of cancer where TEAD1 is downregulated, such as breast, renal, or bladder cancer." (PMID 32293349, 2020). "Considering the regulatory role of YAP1/TEAD4 in KIF4A transcription in esophageal squamous cell carcinoma and the role of TEAD1 in chemoresistance of bladder cancer, we sought to investigate whether YAP1/TEAD1 is involved in KIF4A dysregulation in UBC." (PMID 37039264, 2023).
colon cancer (4 papers, 2014 to 2023). "Analysis using the GEPIA dataset indicates that the YAP1 levels were positively correlated with TEAD1 in colon cancer, rectal cancer and CRC, and surprisingly, the YAP1 and TEAD1 levels were both positively correlated with HIF1A or LDHA." (PMID 33218358, 2020).
cardiac hypertrophy (3 papers, 2022 to 2024). "In this study, we provide significant evidence of a strong association between TEAD1 and pathological cardiac hypertrophy." (PMID 38225750, 2024). "To investigate whether TEAD1 expression is associated with cardiac hypertrophy, we first measured TEAD1 expression levels in heart tissues collected from five healthy controls and five patients diagnosed with hypertrophic cardiomyopathy." (PMID 38225750, 2024). "Finally, adeno‐associated virus serotype 9 is used to construct TEAD1 wild‐type and KR mutant mice and demonstrated that the deSUMOylation of TEAD1 markedly exacerbated cardiomyocyte enlargement in vitro and in a mouse model of cardiac hypertrophy." (PMID 38225750, 2024). "To evaluate the function of TEAD SUMOylation in pathological myocardial hypertrophy in vivo, we pre‐injected mice with CM‐specific adeno‐associated virus (AAV) to deliver TEAD1‐WT and TEAD1‐K177R." (PMID 38225750, 2024). "Mechanistically, Nrf2‐Hmox1 is a potential target of the oxidative stress in cardiac hypertrophy induced by the SUMOylation of TEAD1." (PMID 38225750, 2024). "We observed that TEAD1 expression was dramatically upregulated in cardiac hypertrophy induced by pressure overload in vivo and Ang II in vitro." (PMID 38225750, 2024). "Mechanistically, Nrf2‐Hmox1 is a potential target of oxidative stress in cardiac hypertrophy induced by the SUMOylation of TEAD1." (PMID 38225750, 2024). "We observed that, during cardiac hypertrophy, the modification of TEAD1 by SUMO1 was regulated by the SUMO protease SENP1." (PMID 38225750, 2024). "Gene set enrichment analysis revealed that TEAD1‐WT and TEAD1‐K173R‐regulated DEGs were enriched for cardiac hypertrophy, protein synthesis, and oxidative response." (PMID 38225750, 2024). "Collectively, these findings provide valuable molecular insight into the precise mechanisms through which SUMOylation governs the functional dynamics of TEAD1 during the intricate process of cardiac hypertrophy." (PMID 38225750, 2024). "Based on global gene expression profiling using RNA sequencing, we systematically revealed that the DEGs between TEAD1‐WT and TEAD1‐K173R in NRCMs were related to oxidative stress, cardiac hypertrophy, and protein synthesis." (PMID 38225750, 2024). "Our data revealed that the post‐translational SUMOylation of TEAD1 in response to cardiac hypertrophy stimulation was mediated by the deSUMOylase of SENP1." (PMID 38225750, 2024). "It is discovered that TEAD1 is modified by SUMO1 during cardiac hypertrophy and that the process of deSUMOylation is regulated by SUMO‐specific protease 1 (SENP1)." (PMID 38225750, 2024). "Overall, these data indicate that the SUMOylation of TEAD1 regulates CM enlargement and oxidative stress during cardiac hypertrophy." (PMID 38225750, 2024). "This study aimed to explore the role of TEAD1 in cardiac hypertrophy and to clarify the regulatory role of small ubiquitin‐like modifier (SUMO)‐mediated modifications." (PMID 38225750, 2024). "This study discovers that TEAD1 is an important transcription factor that plays a key regulatory role in cardiac hypertrophy." (PMID 38225750, 2024). "Our study provides the first evidence that the SUMOylation of TEAD1 can significantly modulate TAC‐induced cardiac hypertrophy." (PMID 38225750, 2024). "In addition, we further confirmed that TAC‐induced cardiac hypertrophy in mice limits TEAD1 SUMOylation in vivo using bright‐field PLA." (PMID 38225750, 2024). "Notably, our findings demonstrate that during cardiac hypertrophy, the SUMOylation of TEAD1 plays a critical role in preserving protein stability, facilitating nuclear localization, and enhancing DNA‐binding ability." (PMID 38225750, 2024). "We observed that deSUMOylation of TEAD1 significantly exacerbated CM enlargement both in vitro and in a transverse aortic constriction‐induced mouse model, whereas TEAD1 overexpression effectively attenuated the development of cardiac hypertrophy and remodeling." (PMID 38225750, 2024).
cardiac hypertrophy (continued). "Therefore, targeting the SUMOylation of TEAD1 may represent a promising strategy for treating pathological cardiac hypertrophy." (PMID 38225750, 2024). "To provide further evidence, we assessed the relationship between TEAD1 and SENP1 in NRCM and AC16 cells during Ang II‐induced cardiac hypertrophy." (PMID 38225750, 2024). "Thus, stabilization of HIF-1α, but not TEAD1, may allow YAP to induce salutary actions even during chronic PO by inducing compensatory cardiac hypertrophy." (PMID 35133975, 2022).
cardiomyopathy (3 papers, 2019 to 2023). A disease of the heart muscle or myocardium proper. "Tead1 co-binding with Yap1 is required for proliferation in the perinatal period, as demonstrated by reduced proliferation and cardiomyopathy in mice with conditional loss of Tead1 in cardiomyocytes driven by αMHC-Cre (α-Myosin Heavy Chain)." (PMID 33807107, 2021).
cutaneous melanoma (3 papers, 2018 to 2025). A primary melanoma arising from atypical melanocytes in the skin. "We have previously identified genetic variants of Hippo pathway genes (YAP1 rs11225163, TEAD1 rs7944031 and TEAD4 rs1990330) and revealed that Hippo effector TAZ significantly associated with unfavorable survival in cutaneous melanoma and primary OSCC." (PMID 30459528, 2018). "For example, Hippo pathway genes YAP1, TEAD1, and TEAD4 may jointly modulate the survival of cutaneous melanoma patients." (PMID 35739490, 2022).